MPO (myeloperoxidase)
Diseases named in the same sentence as MPO in open-access papers (continued):
Sharing a sentence is not in itself a finding about the gene and the disease.
Sepsis (continued). "Neutrophils, as primary responders in sepsis, release various components, notably MPO, upon activation." (PMID 38406775, 2023). "Serum lactate dehydrogenase (LDH), malondialdehyde (MDA), and myeloperoxidase (MPO) activities were also significantly increased in the sepsis model." (PMID 38077250, 2023). "In a sepsis model, MPO-KO mice showed marked hypothermia and high mortality after lipopolysaccharide (LPS) injection." (PMID 38037141, 2023). "Neutrophils are the initial responders in sepsis, and once activated, release their granule contents, especially MPO." (PMID 38011291, 2023). "IL-6 and MPO are involved in the altered inflammatory response and they are commonly used as biomarkers for diagnosis and evaluation of severity in sepsis." (PMID 37762478, 2023). "According to the LPS-induced sepsis model, both compounds markedly decreased the MPO, NO, hsCRP, MDA, ALT, and AST levels." (PMID 36768971, 2023). "For our goal to be achieved, a systematic data mining procedure enabled us to identify the upregulation of PDL1 and MPO as good predictors of severity in sepsis (viral and bacterial induced) and septic shock patients." (PMID 36969221, 2023). "MPO, as an index of neutrophil infiltration in sepsis, has consistent patterns with inflammatory cytokines." (PMID 37605037, 2023). "Based on the LPS-induced sepsis model, these agents diminished the MPO, NO, high-sensitivity C-reactive protein (hsCRP), malondialdehyde (MDA), ALT, and AST levels." (PMID 36768971, 2023). "Consistent with our previous studies, patients with sepsis showed increased dsDNA and MPO–DNA complex levels compared with healthy controls." (PMID 37715457, 2023). "A study of 55 critical patients in 2018 showed that the circulating level of the MPO-DNA complex in serum increased rapidly and continuously, indicating the early formation of NETs in sepsis." (PMID 36721229, 2023). "MPO is the major enzyme produced by neutrophils, and it has an antibacterial function during endotoxemia and sepsis." (PMID 36475755, 2023). "Myeloperoxidase activities and mean malondialdehyde concentration of ovarian tissue were lower in nicotinamide riboside-treated group than in sepsis group (P < .05)." (PMID 36648023, 2023). "In another study, MPO levels during the early stages of sepsis were found to be negatively correlated with patient survival." (PMID 36969221, 2023). "PMS remitted sepsis-mediated lung, liver and heart injury through prohibiting MPO/BALF (70.4%/85.6%), AST/ALT (74.7%/62.7%) and CK-MB/CK (62.3%/68.9%) levels." (PMID 37288729, 2023). "Within patients with sepsis, a higher level of MPO–DNA complex was detected in non‐survivors than in survivors." (PMID 37715457, 2023). "For instance, folic acid reduces hippocampal myeloperoxidase activity to alleviate neuroinflammation and improve memory impairment in sepsis‐induced rats." (PMID 36794521, 2023). "Our data show that the MPO activity, iNOS, and lipid peroxides were elevated in the cerebral cortex of mice with sepsis." (PMID 37175808, 2023). "High-dose NR treatment considerably decreased MPO activity that had been raised in the ovary by sepsis." (PMID 36648023, 2023). "At the corresponding time points (8, 12, and 24 h), the activity of MPO in the burn + sepsis + LFM-A13 group was significantly lower than that in the burn + sepsis group." (PMID 35280898, 2022). "Compared with that in the burn+sepsis group, the activity of MPO in the burn + sepsis + LFM-A13 group was significantly lower (P < 0.05) but did not significantly differ at 0 h (P > 0.05)." (PMID 35280898, 2022). "While Delta neutrophil index (DNI) and myeloperoxidase (MPO) are known as a prodiagnostic marker of sepsis, the preclinical evidence of the best marker of sepsis is unclear." (PMID 35334545, 2022). "CLP males treated with ticagrelor or MRS2279 showed a decrease in sepsis-induced MPO levels in lung and kidneys, aggregate formation, and platelet activation as compared to untreated male CLP mice." (PMID 36405709, 2022).
Sepsis (continued). "Here, we show that by controlling fungi and bacteria captured by splenic macrophages, neutrophil-derived myeloperoxidase attenuates sepsis by suppressing histone release." (PMID 35945238, 2022). "Increased MPO expression was detected on the surface of neutrophils from patients with various inflammatory diseases, including sepsis, ischemia-reperfusion injury, or acute coronary syndromes, and correlated with plasma MPO levels." (PMID 36421487, 2022). "Considering that inflammation has a significant effect on the pathogenesis of sepsis, the activity of MPO, a neutrophil infiltration marker, in the liver was assayed to evaluate the anti-inflammatory effect of PSP." (PMID 36144734, 2022). "As the lung is one of the most affected organs during sepsis, we investigated MPO activity in lung tissue as an indication of neutrophil infiltration in the tissue." (PMID 36405709, 2022). "Acknowledging that NETs contain DNA, citH3, and MPO, the plasma contents of NETs in sepsis and COVID-19 patients can be determined by PicoGreen fluorescence assay and ELISA by detecting citH3 and MPO using dsDNA Abs." (PMID 35961978, 2022). "To elucidate the involvement of NETs in sepsis-associated ALI, we measured the levels of cfDNA and MPO-DNA in patients with sepsis and septic ARDS, as well as healthy controls." (PMID 35637949, 2022). "For example, neural MPO concentrations are elevated in models of sepsis and several neurodegenerative disorders." (PMID 36293108, 2022). "In this regard, it is noteworthy that elevation of circulating syndecan-1 was associated with inflammatory biomarkers of neutrophil activation, including MPO, and was predictive of adverse clinical outcomes in patients with sepsis due to pneumonia." (PMID 36119052, 2022). "The increase in MPO-activity/staining seen in animals with CLP-sepsis and the prevention of this effect by PF271 treatment were mirrored by similar effects of CLP and PF271 on iNOS expression." (PMID 35178052, 2022). "Our data suggest for the first time that the purinergic receptor P2Y12 and P2Y1 influence sepsis-induced activity of MPO in lungs and kidneys, circulating cytokines, platelet activation and platelet-leukocyte interaction differently in male and female mice." (PMID 36405709, 2022). "Specifically, we documented that the sepsis-induced increase in MPO activity in renal tissues, was significantly counteracted by ICOS-Fc treatment." (PMID 36119089, 2022). "This is in line with a report showing that nicotine significantly affected MPO activity, contributing to sepsis-induced oxidative multiorgan damage after acute administration." (PMID 36552632, 2022). "The activity of MPO in the burn group was slightly increased compared with that in the sham group, and that in the burn+sepsis group was significantly higher than that in the other two groups and gradually increased over time." (PMID 35280898, 2022). "The detection of MPO activity in the intestinal tissues of mice showed that the activity of MPO in the burn+sepsis group was significantly higher than that in the sham and burn groups and gradually increased over time." (PMID 35280898, 2022). "We found that FA decreased the lung injury score (48% reduction), lung wet/dry weight ratio (33% reduction), and myeloperoxidase activity (58% reduction) in sepsis-induced ALI." (PMID 36433644, 2022). "Mortality, hypothermia and proinflammatory cytokine release after LPS administration are increased in MPO KO mice compared with WTs, suggesting that MPO is beneficial in cases of sepsis." (PMID 36293108, 2022). "In the current study, we discovered that Lav pre-treatment markedly restrained oxidative stress in sepsis-induced rats by reducing MPO activity and MDA content, and elevating SOD and GSH contents." (PMID 35588105, 2022).
Sepsis (continued). "collected statistics of complete blood count, C-reactive protein (CRP), IL-6, levels of cell-free DNA (cfDNA), neutrophil elastase (NE) and myeloperoxidase (MPO) in umbilical cord blood to try to predict the early-onset sepsis." (PMID 35572571, 2022). "The mice under NM treatment revealed a significantly reduced MPO activity compared to the sepsis group, whereas the mice with RM administration showed a slight, non-significant suppression (P ​> ​0.05)." (PMID 35345558, 2022). "These experiments suggested that MPO-derived oxidants are critical in controlling the hyphal form to avert the rapid onset of sepsis." (PMID 35945238, 2022). "Elevation of neutrophil activation markers HBP and MPO was an early event in the evolution of sepsis, lasting beyond the subsidence of the pro-inflammatory cytokine reaction." (PMID 33461369, 2021). "On the other hand, it is interesting to further explore the function of MPO in the pediatric sepsis study." (PMID 33748037, 2021). "As compared to the values of the saline-treated sepsis groups, all the treatments resulted in significantly lower CitH3 and MPO values, whereas IL-1β was lower only in response to SZR-104 treatment." (PMID 34475875, 2021). "We found that systemic neutrophil activation, measured by HBP and MPO, occurs early and lasts for at least 24 h in the evolution of sepsis." (PMID 33461369, 2021). "Using two potential target genes (MMP9 and MPO), we established a logistic regression model aiming for pediatric sepsis prediction." (PMID 33748037, 2021). "These evidences highlighted the importance of understanding the relation between the MPO gene family pathway and pediatric sepsis, which initiated a tremendous starting point for the following study." (PMID 33748037, 2021). "In an observational study, we measured heparin-binding protein (HBP), myeloperoxidase (MPO), IL-6 and IL-8 in 167 sepsis patients on intensive care unit admission." (PMID 33461369, 2021). "In this study comprising adult critically ill septic patients we found that intravascular neutrophil activation measured by plasma HBP and MPO concentrations had steadily elevated before the onset of sepsis and remained elevated up to 24 h." (PMID 33461369, 2021). "These elevations were not present in the cerebellum in any of the treated groups, and all three treatments resulted in significantly lower tissue MPO values than untreated sepsis." (PMID 34475875, 2021). "Plasma levels of CitH3, MPO and IL-1β were elevated in sepsis but were ameliorated by KYNA and its synthetic analogues." (PMID 34475875, 2021). "The sepsis-induced deterioration in tissue CI–CII-linked OXPHOS and BBB parameters as well as the increase in tissue MPO content were positively affected by KYNA/KYNA analogues." (PMID 34475875, 2021). "There are plenty of data showing that under inflammatory conditions, MPO is spilled into the circulation, as elevated free MPO plasma levels were detected in many pathological conditions including sepsis and acute coronary syndromes." (PMID 33959129, 2021). "Up-regulation of miR-10a increased ROS, TNF-α, IL-6, and MPO, and downregulation reduced sepsis-induced liver injury." (PMID 34956235, 2021). "We previously reported that eCIRP induces neutrophils to form extracellular traps in sepsis, containing citrullinated histone H3, MPO, and extracellular DNA, activating the immune system to promote inflammation." (PMID 35003095, 2021). "In this study, kidney expression of CD68 and EMR-1 was elevated and MPO activity was increased in the obese groups with sepsis, suggesting that macrophage and neutrophil infiltration and inflammation occurred during the experimental period." (PMID 33859538, 2021). "Recent studies have found that FO enriched lipid emulsion is able to prevent long-term cognitive impairment caused by sepsis, by protecting the BBB as well as inhibiting the activity of MPO." (PMID 34804998, 2021).
Sepsis (continued). "The sepsis-induced increases in MPO and CitH3 levels in plasma were significantly reduced by KYNA and its analogues, and IL-1β plasma levels were also positively influenced by SZR-104." (PMID 34475875, 2021). "A previous study showed that MPO can be used as a marker of neutrophil infiltration and the severity of inflammation in sepsis patients." (PMID 33859538, 2021). "In other words, plasma concentrations of neutrophil activation biomarkers HBP and MPO were markedly increased early in the course of sepsis." (PMID 33461369, 2021). "The miR-199a inhibition during sepsis decreases the release of pro-inflammatory cytokines from AMs, MPO activity, the incidence of vascular leakage from pulmonary endothelium." (PMID 32849610, 2020). "On the other hand, in human sepsis patients diminished MPO expression was identified as the best predictor to identify a subgroup of patients at high risk of death." (PMID 32050431, 2020). "The pulmonary B1a cells exert a protective role in cecal-ligation and puncture (CLP)-induced sepsis via inhibiting neutrophil infiltration and MPO production in the lungs." (PMID 32849610, 2020). "The remaining six studies included in this review analyzed the presence of molecules potentially associated with neutrophil dysfunction in sepsis, such as pentraxin 3 (PTX3), ROS, and myeloperoxidase." (PMID 33111742, 2020). "To confirm the histological findings of liver neutrophil infiltration in KO mice after sepsis we measured the activity of MPO, a neutrophil lysosomal enzyme." (PMID 32117320, 2020). "As an indicator of neutrophilic infiltration in sepsis, the MPO activity in LIGHT KO mice was also remarkably attenuated compared to that in WT mice." (PMID 32881263, 2020). "In several disease scenarios and sepsis, the involvement of MPO in the pathological process is discussed." (PMID 33137905, 2020). "The AM depletion attenuates the sepsis-induced increase in pulmonary microvascular protein leak and MPO activity that depends on the activation of iNOS." (PMID 32849610, 2020). "Compared with the sepsis group, the MPO levels in the lungs of the sepsis+MLD group showed an apparent downward trend (p > 0.05)." (PMID 33145344, 2020). "The concentrations of cardiac 2-ClHDA observed here are slightly lower as reported for a cecal slurry-induced rat sepsis model, most likely due to the lower MPO activity in mice." (PMID 33287422, 2020). "During the present study, we sought evidence for MPO-mediated plasmalogen modification in an LPS-induced murine endotoxemia model that reflects some characteristic features observed in murine sepsis models." (PMID 33287422, 2020). "Patients with sepsis or with septic shock show higher plasma levels of MPO in comparison to patients with systemic inflammatory response syndrome without infection." (PMID 33137905, 2020). "The increased MPO activity in the heart tissue of CLP-induced sepsis mice was correlated with the increased inflammatory cell infiltration, especially neutrophils, in the heart tissue." (PMID 32423469, 2020). "The animals 18 h after CLP-induced sepsis exhibited markedly increased staining for myeloperoxidase (MPO), an index of neutrophil infiltration, in lung sections." (PMID 32943679, 2020). "Here, we demonstrated elevated NET formation in the lungs during polymicrobial sepsis by flow cytometry, using two key components of NETs, citrullinated histone H3 and MPO." (PMID 31000768, 2019). "Attenuation of sepsis − induced lung injury has been correlated with reduced levels of neutrophil infiltration and chemokine expression by using MPO as a marker in several reports." (PMID 31817302, 2019). "The DEGs (IL1R2, ARG1, FCGR1A, MMP9, ELANE, and MPO) that were common on day1 and day3 of sepsis, with at least 2.0-fold upregulation, were selected for constructing and visualizing the PPI network using Cytoscape." (PMID 31817302, 2019).
Sepsis (continued). "In a clinical study, the levels of neutrophil-derived circulating free DNA (cf-DNA/NETs) have been shown to directly correlate with multiple organ dysfunction score, sepsis-related organ failure assessment, leukocyte counts, and MPO levels." (PMID 31736963, 2019). "One major pathway regulated by MPO is the degradation of melatonin, which is reduced during sepsis, with MPO playing a role in this process." (PMID 29540208, 2018). "While this study revealed a significant increase in both cf-DNA and MPO-DNA levels on day 1 of sepsis, the cf-DNA level declined rapidly and MPO-DNA decreased more slowly." (PMID 30005596, 2018). "Although elevation of the plasma level of cell-free DNA (cf-DNA) has been reported in sepsis patients, there has been little direct measurement of circulating free NETs such as myeloperoxidase-conjugated DNA (MPO-DNA)." (PMID 30005596, 2018). "Regarding the prediction of 28-day mortality, the area under the ROC curve for MPO-DNA on days 1, 3, and 7 of sepsis was 0.66 (p = 0.054, 95% CI 0.51–0.82), 0.74 (p = 0.005, 95% CI 0.33–0.77), and 0.83 (p = 0.0004, 95% CI 0.70–0.97), respectively." (PMID 30005596, 2018). "The attenuation of sepsis-induced lung injury was correlated with reduced levels of chemokine expression, neutrophil infiltration as assessed by MPO, and cellular apoptosis through the down-regulation of caspase-3 activity." (PMID 30134811, 2018). "B-1a cell treatment significantly down-regulated MPO levels in the lungs compared to PBS-treated mice in sepsis." (PMID 30134811, 2018). "The increase in circulating MPO-DNA in patients with septic shock indicates acceleration of NET formation in the early stages of sepsis." (PMID 30005596, 2018). "During sepsis, ROS and MPO production exceeds antioxidant defenses and leads to a state of oxidative stress that fuels inflammation and causes direct mitochondrial damages, which is suggested to play a central role in sepsis-induced organ dysfunction." (PMID 28694565, 2017). "The relationship between sepsis and elevated MPO levels as found in our study can be explained by the leakage of MPO into the plasma when neutrophils phagocyte bacteria." (PMID 28916973, 2017). "The sepsis KO mice showed significantly less MPO activity in the liver and lungs compared with the WT sepsis mice." (PMID 27518439, 2016). "The sepsis-induced increase in lung staining of MPO, an index of neutrophil infiltration, was significantly reduced in HDC−/− mice in comparison with WT controls." (PMID 27822777, 2016). "Conversely, CSE KO mice had less liver and lung injury and reduced inflammation following CLP-induced sepsis as evidenced by decreased levels of H2S synthesizing activity, MPO activity, and pro-inflammatory cytokines/chemokines production." (PMID 27518439, 2016). "PMN activation as assessed by MPO activity in lung tissue (frame F) 36 hours after blunt chest trauma and 12 hours after induction of sepsis, was increased after DH in wt and C5-/- mice." (PMID 27437704, 2016). "ROS production by PMN isolated from severe sepsis patients, and elevated MPO concentrations in blood plasma isolated from septic patients have both been reported." (PMID 25882865, 2015). "In former studies of our workgroup, we found elevated levels of malondialdehyde (MDA) and myeloperoxidase (MPO) in the early phase of sepsis." (PMID 26576228, 2015). "Sepsis increased MPO activity in the lung, but the observed difference only reached statistical significance between the isoflurane + CLP and the isoflurane-sham groups (1.7-fold increase, P = 0.02)." (PMID 25887642, 2015). "Similar levels of MPO activity were observed in the lungs of WT, Nod1/Nod2- and Rip2-deficient mice 24 h after CLP-induced severe sepsis, further confirming that these pathogen sensors are not relevant to neutrophil sequestration in the lung." (PMID 25084278, 2014).